AR (androgen receptor)
Diseases named in the same sentence as AR in open-access papers (continued):
Sharing a sentence is not in itself a finding about the gene and the disease.
renal cell carcinoma (continued). "Androgen receptor (AR) signaling may promote renal cell carcinoma (RCC) progression via altered HIF-2α/VEGF signaling." (PMID 27848972, 2016). "Recent studies have demonstrated that the androgen receptor (AR) could play important roles to promote renal cell carcinoma (RCC) cell proliferation, and other studies have also indicated that suppressing the argininosuccinate synthase 1 (ASS1) could promote proliferation of various tumors." (PMID 31000693, 2019). "Androgen receptor is expressed in the distal and proximal tubules of normal kidneys and is expressed in approximately 15% to 42% of renal cell carcinomas (RCC)." (PMID 28085048, 2017). "In renal cell carcinoma, IGFL2-AS1 knockdown has been shown to suppress the expression and activation of the androgen receptor, leading to the downregulation of vascular mimicry and increased efficacy of PAZ." (PMID 39033109, 2024). "In renal cell carcinoma, highly expressed HOTAIR interacts with the androgen receptor (AR) and cooperatively promotes GLI2 transcription by binding to its promoter." (PMID 34635646, 2021). "Immunohistochemical profile of MC includes positivity for CK7, CAM5.2, EMA, CEA, GCDFP-15 (gross cystic disease fluid protein 15), RCC (renal cell carcinoma) antigen, WT1 (Wilms’ tumor protein), ER, PR, and AR." (PMID 34064849, 2021). "Furthermore, studies on RCC cell lines demonstrated a potential positive feedback loop between sunitinib and lncRNA Suppressing Androgen Receptor in Renal Cell Carcinoma (SARCC)." (PMID 32784737, 2020). "In this pathway, LncRNA-suppressing androgen receptor in renal cell carcinoma (SARCC) serves as a critical regulator, it connects with the AR/HIF2A/MYC axis to regulate cell growth in response to hypoxia." (PMID 28467794, 2017). "Targeting AR and UCHL1 may serve as a novel target for Xp11.2 translocation renal cell carcinoma therapy." (PMID 35452181, 2022). "For instance, in kidneys without RCC the location of AR is cytoplasmic, while in renal cell carcinoma it is nuclear." (PMID 31100850, 2019).
complete androgen insensitivity syndrome (44 papers, 2007 to 2026). "In summary, the child in this case was diagnosed with Complete Androgen Insensitivity Syndrome (CAIS) caused by an Exon 1 deletion mutation in the AR gene." (PMID 40352611, 2025). "In complete androgen insensitivity syndrome (cAIS), mutations of the androgen receptor (AR) can be seen in 95% of all patients, whereas in partial androgen insensitivity syndrome it can be detected in up to 50%." (PMID 34070473, 2021). "DSD due to complete loss of function of the AR is termed Complete Androgen Insensitivity Syndrome (CAIS), whereas mutations that retain some residual function result in Partial Androgen Insensitivity Syndrome (PAIS)." (PMID 32224856, 2020). "Complete androgen insensitivity syndrome (CAIS) is an X-linked recessive genetic disorder resulting from maternally inherited or de novo mutations involving the androgen receptor gene, situated in the Xq11-q12 region." (PMID 30970592, 2019). "Most important, related mutations of the AR gene in humans, also known as complete androgen insensitivity syndrome (CAIS), suggest that functional AR are required to masculinize the human brain." (PMID 29107990, 2017). "Regarding the role of the androgen receptor pathway in the development of gender identity, interesting evidence may come from 46, XY individuals with Complete Androgen Insensitivity Syndrome (CAIS)." (PMID 32204531, 2020).
androgenetic alopecia (43 papers, 2009 to 2025). "The biological mechanisms linking androgenic alopecia and PrCa likely involve systemic and local androgens metabolism, androgen receptor (AR) signaling, and shared genetic susceptibility." (PMID 41228372, 2025). "Androgenetic alopecia (AGA) is associated with dihydrotestosterone (DHT)-induced apoptosis in human dermal papilla cells (HDPCs) via androgen receptor (AR) upregulation." (PMID 40699835, 2025). "Specific AR gene polymorphisms, such as SNP rs6152 in the first exon of the AR gene, have been associated with AR expression and the development of androgenetic alopecia and BPH." (PMID 38778357, 2024). "Changes in the androgen receptor (AR) gene and 5-alpha reductase gene are clinically significant, whereas triple repeat polymorphisms and single nucleotide polymorphisms are associated with androgenic alopecia." (PMID 40536553, 2025). "Additionally, the polymorphisms of the AR genes have been described, among which those that increase the probability of the occurrence of the post-finasteride syndrome or androgenic alopecia have been identified." (PMID 34449557, 2021). "Although many different pathways have been implicated in the development of androgenetic alopecia, their results suggest that in addition to the androgen receptor pathway, for which they confirm a prominent function, the Wnt and apoptosis pathways play a fundamental role." (PMID 30965624, 2019). "The functional polymorphism that explains the established association of the androgen receptor (AR) with androgenetic alopecia (AGA) remains unidentified, but Copy Number Variation (CNV) might be relevant." (PMID 19340294, 2009). "In patients with androgenetic alopecia, the excessive activation of the androgen receptor causes follicular shrinkage through a gradually shorter anagen phase, leading to thinner and shorter hair follicles that may not even eventually pass through the epidermis in the end." (PMID 37182050, 2023). "This miniperspective highlights key advances inthe development of topical PROTACs, exemplified by AH-001 and GT20029, androgen receptor degraders, both in clinicaltrials for androgenetic alopecia, with GT20029 also evaluatedfor acne." (PMID 41255358, 2025). "ASC-J9, an AR degrader developed by AndroScience, has entered phase II clinical trials for potential clinical use for men with androgenetic alopecia." (PMID 38339414, 2024). "In patients with androgenetic alopecia, the expression of AR and DKK-1 in HDPCs within the balding region is higher compared to the non-balding region, inhibiting the Wnt/β-catenin regulatory pathway and resulting in hair thinning." (PMID 38398550, 2024). "Scutellaria baicalensis Georgi extract has been reported to affect the function of the liver, and its active compound, baicalin, was indicated to inhibit androgen receptor translocation, which is important for the prevention of androgenetic alopecia." (PMID 36440360, 2022). "Drugs such as clascoterone are antagonists of the androgen receptor (AR) for the treatment of androgen-dependent skin diseases, including androgenetic alopecia and acne." (PMID 34668739, 2021). "In androgenetic alopecia (AGA), elevated androgen receptor (AR) in DP cells is one of the causal factors for AGA." (PMID 32953277, 2020). "The importance of the gene encoding the androgen receptor (AR; NCBI NM_000044) in the development of androgenetic alopecia (AGA; OMIM %300710) is now well established." (PMID 19340294, 2009). "Additionally, four other AR PROTACs (three for metastatic castration-resistant prostate cancer, one for androgenic alopecia and acne) have entered phase I clinical trials." (PMID 38339414, 2024). "Previous studies also suggest that the androgen receptor (AR), which is specifically expressed in DPCs in the skin, may be involved in androgenic alopecia." (PMID 39452150, 2024).
androgenetic alopecia (continued). "Therefore, the upregulation of AR induced by DHT plays an important role in androgen alopecia, but NMN can effectively decrease AR expression in HDPCs, potentially contributing to the regulation of hair growth in AGA." (PMID 38398550, 2024). "Candidates for androgenetic alopecia are the genes AR and 5-alpha reductase." (PMID 37818522, 2023). "The AR gene's relationship to male pattern baldness has been the subject of several investigations." (PMID 37818522, 2023). "Androgenetic alopecia (AGA) affects more than half of the adult population worldwide and is primarily caused by the binding of dihydrotestosterone (DHT) to androgen receptors (AR)." (PMID 37496996, 2023). "A topical AR-PROTAC compound (GT20029) in phase I clinical trials could treat patients with androgenetic alopecia and acne (NCT05428449)." (PMID 36499765, 2022). "Particularly, in the case of androgenetic alopecia, ectopic activation of androgen receptor signaling responding to dihydrotestosterone in the HF, mainly in the DP, alters the expression of hair growth-related paracrine factors (such as DKK1, Wnts, and TGF-βs)." (PMID 29761053, 2018). "Onset of male pattern baldness could be influenced by EDA2R via activation of nuclear proto-oncoprotein c-Jun, which is linked to transcription activation of AR." (PMID 28196072, 2017). "In patients with androgenetic alopecia, the level of AR mRNA in DPCs is higher than in normal people, which results in sustained binding of DHT to the AR of DPCs." (PMID 40521098, 2025). "Although minoxidil has been used for more than two decades to treat androgenetic alopecia (AGA), an androgen-androgen receptor (AR) pathway-dominant disease, its precise mechanism of action remains elusive." (PMID 24742982, 2014). "After extensive simulation studies we investigated three real life scenarios: First, the interplay between androgen receptor (AR) and HDAC9 in the context of male pattern baldness." (PMID 23627667, 2013). "A meta-analysis of 15 different randomized, placebo-controlled trials of 4,495 subjects revealed a 1.57-fold (95% CI 1.19–2.08) increase in the risk of sexual dysfunction as compared to placebo in both patients receiving 5 AR inhibitors for BPH and androgenic alopecia (AGA)." (PMID 40490610, 2025).
colorectal cancer (43 papers, 2012 to 2025). A primary or metastatic malignant neoplasm that affects the colon or rectum. "In human colorectal cancer and skin cutaneous melanoma, AR expression in CD8+ T cells was associated with their exhaustion." (PMID 39682229, 2024). "Further large epidemiological studies as well as functional studies are needed to elucidate the role of ESR2 and AR polymorphisms in colorectal cancer development and prognosis." (PMID 25376484, 2014). "We therefore assessed the association of repeat polymorphisms in the estrogen receptor β gene (ESR2) and the androgen receptor gene (AR) with colorectal cancer risk and prognosis." (PMID 25376484, 2014). "We did not observe significant associations between the number of CAG repeats in AR and colorectal cancer risk." (PMID 25376484, 2014). "Therefore, genetic variation in ESR2 and AR may affect the action of sex steroids on colonic epithelium and consequently influence the colorectal cancer susceptibility and prognosis." (PMID 25376484, 2014). "Compared with the conventional BET inhibitors, ARV-771 has higher efficiency in colorectal cancer cell lines, and it can simultaneously inhibit the expression of AR protein and the transmission of the AR signal." (PMID 36557960, 2022). "The role of androgens and AR mutations in the development of CRC is unclear although the presence of AR has been demonstrated in normal colonic mucosa and colorectal cancer." (PMID 35173303, 2022). "In summary, these results provide evidence that AR decoction inhibited the proliferation and migration of colorectal cancer cells by inhibiting Wnt5/β-catenin." (PMID 34991661, 2022). "Patients with higher levels of AR expression had significantly worse survival and AR expression may be a prognostic marker for colorectal cancer." (PMID 38115900, 2023). "Importantly, in male colorectal cancer cells, the AR-dependent TUBB3 regulatory pathway is constitutively activated via testicular androgen, while in colorectal cancer cell lines derived from women TUBB3 is only inducible upon serum starvation." (PMID 35573698, 2022). "However, suggestive significance was found between PIK3CB and colorectal cancer on the left side (p = 0.0007), androgen receptor (AR) and female gender (p = 0.0002), TGM7 and young patient (p = 0.002), and EXT1 and late stage." (PMID 34207827, 2021). "Previous reports have suggested that AR was correlated with the upregulation of TUBB3 expression in colorectal cancer, and activated AR signaling could enhance tubulin expression." (PMID 34318630, 2021). "AR protein has been shown to be expressed in normal colorectal mucosa and in most colorectal cancer, supporting that CRC expressing the AR receptor may respond to mitogenic effects of the hormone." (PMID 22496748, 2012). "Nevertheless, this differential mutational profile suggests that IKKα signalling may be occurring through two independent mechanisms, one which is associated with AR mutation and the other which is associated with alterations in KRAS and inferior survival outcomes in primary colorectal cancer." (PMID 35173303, 2022). "However, the fact that normal colorectal mucosa expresses AR might blunt the usefulness of AR inhibitors in colorectal cancer." (PMID 25595907, 2015). "Whether the AR CAG repeat is associated with colorectal cancer prognosis has not been investigated so far." (PMID 25376484, 2014). "Overall, the current results provide evidence that AR decoction inhibits the expression of ARF6 and N-Cadnerin in colorectal cancer cells by inhibiting Wnt5/β-catenin." (PMID 34991661, 2022). "We found no indication for an association between the AR CAG repeat polymorphisms and risk of colorectal cancer." (PMID 25376484, 2014). "However, while a role for the AR in colorectal cancer has been proposed, we have previously shown that the AR is not expressed in colonic epithelial cells." (PMID 30093969, 2018).
acne (41 papers, 2013 to 2025). An inflammatory process of the sebaceous glands which is characterized by comedones, nodules, papules and/or pustules on the skin. "In preclinical models, HA-P5 nanoparticles simultaneously suppressed fibroblast growth factor receptor-2 (FGFR2) and androgen receptor (AR) signaling in sebocytes, reduced sebum synthesis, and reversed acne-associated transcriptomic alterations." (PMID 41471115, 2025). "For example, recent studies have detected additional factors contributing to PCOS-associated acne, like genetic predispositions, which can modulate androgen receptor sensitivity and sebaceous gland responsiveness." (PMID 41473651, 2025). "al, a study of European Americans found a significant association between teenagers with severe acne and a Myc protooncogene related to upregulation of AR on the chromosome 8 q24 region." (PMID 34207527, 2021). "Nuclear FoxO1 deficiency has been linked to all major factors of acne pathogenesis, that is, androgen receptor transactivation, comedogenesis, increased sebaceous lipogenesis, and follicular inflammation." (PMID 27803511, 2016). "End organ receptor sensitivity of the AR is particularly relevant to the processes underlying acne." (PMID 34207527, 2021). "However, SP also antagonizes the androgen receptor, and thus SP has also been shown to be effective in the treatment of acne, hair loss, and hirsutism in women." (PMID 32414008, 2020). "However, AR antagonism ultimately led to the use of SP in a variety of for androgen-associated skin conditions, including acne and hair growth dysfunction." (PMID 32414008, 2020). "Clascoterone, a pioneering topical androgen receptor inhibitor, was approved in 2020 for the treatment of acne in patients aged 12 and older." (PMID 40887887, 2025). "Some target genes were likely involved in acne development, including AR, IGF1/IGF1R, mTOR, GATA6, Wnt, IL6, FOXO1, PIK3, MYC." (PMID 40625748, 2025). "This dual modulation of FGFR2/AR signaling underscores the potential of HA derivatives as safe, biologically active agents for acne treatment." (PMID 41471115, 2025). "In our previous research, we demonstrated that P5 inhibits FGFR2 and androgen receptor (AR) signaling, suggesting its potential as an acne antagonist." (PMID 39859240, 2025). "In adult female acne, spironolactone, an androgen receptor blocker, has demonstrated efficacy as an off‐label treatment for acne." (PMID 40823723, 2025). "Spironolactone is a peripheral antiandrogen drug that acts as an effective competitive inhibitor of dihydrotestosterone at the skin androgen receptor to reduce the secretion of sebum and thereby improve acne." (PMID 40326775, 2025). "IGF-1 is another crucial hormonal driver, influencing acne by downregulating the nuclear transcription factor forkhead box protein O1 (FoxO1), which, in turn, increases lipogenesis and androgen receptor transduction." (PMID 38791344, 2024). "For instance, variations in genes related to the androgen receptor can lead to increased sebum production, a key factor in acne development." (PMID 38791344, 2024). "In the treatment of acne vulgaris, drugs that inhibit androgen receptor signaling are also currently selected." (PMID 38371936, 2024). "Extensive studies have shown that AR signalling stimulates sebum secretion in hair follicles and drives the formation and development of acne." (PMID 36803994, 2023). "AZD4547 treatment, on the one hand, decreased FGFRs and AR signalling; however, on the other hand, it increased the formation of androgen, demonstrating the role of fence-sitters in acne therapy." (PMID 36803994, 2023). "In this manner, FGFR signalling is one of the downstream effects of AR signalling during the formation of acne lesions." (PMID 36803994, 2023). "DNG has low androgen receptor activity and some antiandrogenic activity, which explains the limited androgen-like side effects, such as weight gain, acne, alopecia and hirsutism." (PMID 37587520, 2023).